ADCY2 (adenylate cyclase 2)
Description:
Catalyzes the formation of the signaling molecule cAMP in response to G protein signaling. Down-stream signaling cascades mediate changes in gene expression patterns and lead to increased IL6 production. Functions in signaling cascades downstream of the muscarinic acetylcholine receptors (By similarity).
Synonyms: KIAA1060; HBAC2; AC2
Tractability: Small molecule: a high-quality ligand is known. Antibody: UniProt places it where antibodies can reach, with high confidence; its Gene Ontology location is reachable by antibodies, with high confidence; UniProt predicts a signal peptide or a membrane-spanning region. PROTAC: ubiquitination databases record sites on it; a small molecule that binds it is known.
Target class: Enzyme; Lyase
Gene: Protein-coding gene on chromosome 5 (7,395,681 to 7,830,081, forward strand). Ensembl gene ENSG00000078295.
Subcellular location: Membrane; Cell membrane; Cytoplasm
Subcellular location (Human Protein Atlas): Golgi apparatus; Vesicles; Nuclear membrane; Primary cilium
Pathways (Reactome):
Signal Transduction: Adenylate cyclase activating pathway; G alpha (i) signalling events; G alpha (s) signalling events; G alpha (z) signalling events; GPER1 signaling; Hedgehog 'off' state; PKA activation
Disease: ADORA2B mediated anti-inflammatory cytokines production; FCGR3A-mediated IL10 synthesis
Metabolism: Glucagon signaling in metabolic regulation; PKA activation in glucagon signalling
Cellular responses to stimuli: High laminar flow shear stress activates signaling by PIEZO1 and PECAM1:CDH5:KDR in endothelial cells
Neuronal System: Adenylate cyclase inhibitory pathway
Transport of small molecules: Vasopressin regulates renal water homeostasis via Aquaporins
Gene Ontology:
Molecular function: adenylate cyclase activity; adenylate cyclase binding; magnesium ion binding; manganese ion binding; phosphorus-oxygen lyase activity
Biological process: adenylate cyclase-activating G protein-coupled receptor signaling pathway; adenylate cyclase-modulating G protein-coupled receptor signaling pathway; cAMP biosynthetic process; cellular response to forskolin; cellular response to glucagon stimulus; renal water homeostasis; vascular endothelial cell response to laminar fluid shear stress; cyclic nucleotide biosynthetic process; intracellular signal transduction
Cellular component: cytoplasm; membrane; plasma membrane; dendrite; membrane raft
Genetic constraint (gnomAD): Loss-of-function variants: 25 observed, 106.13 expected, observed/expected ratio (o/e) 0.24, 90% interval 0.17 to 0.33. The upper end of that interval is the gene's LOEUF score, 0.33, which puts it in group 1 of 6, group 1 being the genes least tolerant of losing a copy. Missense variants: 869 observed, 1,370.7 expected, observed/expected ratio (o/e) 0.63, 90% interval 0.6 to 0.67. Synonymous variants: 503 observed, 534.22 expected, observed/expected ratio (o/e) 0.94, 90% interval 0.87 to 1.01.
Homologues: Orthologues: chimpanzee ADCY2 (99% identical), macaque ADCY2 (99% identical), guinea pig ADCY2 (97% identical), dog ADCY2 (96% identical), pig ADCY2 (96% identical), rat Adcy2 (96% identical), mouse Adcy2 (96% identical), rabbit ADCY2 (91% identical), zebrafish adcy2a (83% identical), zebrafish adcy2b (78% identical). Paralogues in human: ADCY4 (56% identical), ADCY7 (54% identical), ADCY6 (39% identical), ADCY5 (38% identical), ADCY8 (36% identical), ADCY1 (34% identical), ADCY3 (33% identical), ADCY9 (28% identical), GUCY2F (16% identical), GUCY2D (16% identical), NPR1 (16% identical), NPR2 (15% identical), and 5 more.